MUC5AC (mucin 5AC, oligomeric mucus/gel-forming)
Diseases named in the same sentence as MUC5AC in open-access papers (continued):
Sharing a sentence is not in itself a finding about the gene and the disease.
COVID-19 (21 papers, 2021 to 2024). A disease caused by infection with severe acute respiratory syndrome coronavirus 2. "Evidence suggests that the considerable elevation of IL-6 cytokines in severe COVID-19 patients is linked to massive mucus production by stimulating the expression of the two predominant mucin genes (MUC5AC and MUC5B) in tracheobronchial epithelial cells." (PMID 34046036, 2021). "Glycoproteins in the mucus such as Muc5ac play a role in making more difficult to COVID-19 to arrive to the distal airway and to cause an infection." (PMID 34946251, 2021). "In the course of COVID-19, elevated levels of gel-forming MUC5AC and shed MUC1 can be detected in sputum aspirated from the trachea of patients and high production of MUC5AC was observed in SARS-CoV-2 infected primary respiratory cultures." (PMID 37561789, 2023). "Increased MUC1 and MUC5AC mucin protein levels were found in the airway mucus of critically ill COVID-19 patients." (PMID 37175509, 2023). "There are also some preliminary data that suggests MUC5AC is upregulated in the airway mucus of patients with severe COVID-19, although these studies were conducted using small sample sizes." (PMID 35768473, 2022). "In contrast, a recent study has described elevated MUC1 and MUC5AC protein levels in airway mucus of critically ill COVID-19 patients." (PMID 35131898, 2022). "Additionally, our findings that several of the SARS-CoV-2 proteins can reduce cellular levels of MUC5AC/B, possibly via increased secretion, provides insight into one of the mechanisms by which the virus causes devastation of the respiratory system in the most severe COVID-19 cases." (PMID 35337019, 2022). "Two of the genes, MUC5AC and FLNA, have already been linked to the COVID-19 host response to different degrees." (PMID 34828448, 2021). "Indeed, the protein levels of MUC1 and MUC5AC were elevated in airway mucus of patients with COVID-19 compared to control individuals, and a high production of MUC5AC was observed in SARS-CoV-2-infected primary respiratory." (PMID 38392851, 2024). "For example, ciliated and TP63/MUC5AC networks were enriched in some COVID-19 lungs, which are consistent with histopathologic IPF features that exhibit infiltration of fibrotic alveoli with airway basal cells and “honeycombing cysts” lined by mucus producing ciliated epithelia." (PMID 35857635, 2022). "For sex-specific GWAS, a GWS association specific to males was found between MUC5AC and MUC5B, which highly colocalizes with a MUC5B eQTL in lung tissue and many studies have linked this variant to pulmonary disease like idiopathic pulmonary fibrosis and COVID-19." (PMID 39132489, 2024). "Moreover, SA100A12, together with S100A8 and S100A9, which are also both released by neutrophils, can activate airway epithelial cells to produce MUC5AC, a major mucin protein in the respiratory tract, partly interoperating the excessive mucus discovered in the necropsy of COVID-19 patients." (PMID 34457122, 2021). "A recent study compared levels of MUC5AC, MUC1 and MUC1-CT between critical ill COVID-19 patients and healthy controls, finding a significantly higher level of those proteins in the patients’ mucus." (PMID 34828448, 2021). "Consistently, the upregulation of mucin 5AC (MUC5AC), a major component of secreted mucins, has also been found in club cells from COVID-19 patients." (PMID 34471261, 2021). "The composition of sputum in samples from patients with asthma, chronic obstructive pulmonary disease, cystic fibrosis, COVID-19, and other respiratory diseases share similarities, containing double-stranded RNA, mucins (mainly MUC1, MUC5AC, and MUC5B), cell debris, and lipids." (PMID 39337895, 2024). "In our study, dexamethasone reduced cytokines and MUC5AC/5B expression induced by SARS-CoV-2 spike RBD protein, providing experimental evidence that supports the clinical results of dexamethasone treatment for COVID-19 patients." (PMID 35692597, 2022).
COVID-19 (continued). "In large airway tissues, genes related to the mucosal layer (MUC4, MUC5AC, MUC5B) as well as cytokine-mediated signaling pathway genes (CCL20, CXCL1, CXCL6, CXCL6, MMP1) and type I interferon genes (IFIT3, ISG15, STAT1, MX1) were upregulated in COVID-19." (PMID 35233546, 2022).
allergic asthma (19 papers, 2017 to 2025). A asthma with a basis in a pathological type I hypersensitivity reaction. "Six of the hub genes were markedly elevated in murine asthmatic lungs and were positively associated with IL-5, IL-13 and MUC5AC, which are the key mediators of allergic asthma." (PMID 36211429, 2022). "MX1, RSAD2, IFIT1, IFI27, OAS3, and SAMD9L were markedly elevated in HDM-treated mice and positively associated with IL-5, IL-13 and MUC5AC (key mediators of allergic asthma)." (PMID 36211429, 2022). "It is well known that the expression of MUC5AC in AECs increased obviously in allergic asthma patients." (PMID 34975337, 2022). "The p65-p50 dimer of NF-κB is then translocated into the nucleus where it binds to DNA to regulate the expression of Th2 cytokines and MUC5AC in allergic asthma." (PMID 33643046, 2021). "Additionally, IL-13 has been shown to cause mucus hypersecretion, contributing the pathophysiology of allergic asthma, as measured by MUC5AC gene expression." (PMID 38706568, 2024). "The same authors showed that blocking the activity of pulmonary sensory neurons and the subsequent release of substance P during allergic asthma was sufficient to reduce allergy-induced goblet cell hyperplasia and hypersecretion of Muc5AC, a mucin that contributes to airway hyperactivity." (PMID 38626267, 2024). "Furthermore, MX1, RSAD2, IFIT1, IFI27, OAS3, and SAMD9L levels correlated positively with IL-5, IL-13, and MUC5AC levels, which are the key mediators of allergic asthma." (PMID 36211429, 2022). "MUC5AC expression is increased in goblet cells, leading to airway limitation in allergic asthma." (PMID 32605045, 2020). "The phosphorylation of MAPKs is found to induce the activation of AP-1, such as c-Jun, and c-Fos, which produce MUC5AC and Th2 cytokine in the OVA-challenged allergic asthma model." (PMID 32605045, 2020). "Although a single exposure to ODE did not impact mucin levels in the airway, it has been demonstrated that repetitive ODE exposure increases Muc5ac expression but that this expression is not at the magnitude seen in experimental allergic asthma models." (PMID 30845921, 2019). "Without being involved in the baseline HDM-induced allergic asthma, IL-1β signalling was required to induce neutrophil chemotactic factors, IL-33, and Muc5ac expression at viral stimulus-induced exacerbation." (PMID 29361942, 2018). "Thus, we concluded that MUC5AC expression is regulated by sNASP/TRAF6 signaling via TLR2 and TLR4, which may provide a novel therapeutic strategy for allergic asthma." (PMID 36012669, 2022). "MUC5B, ORMDL3, MUC5AC, CHI3L1, CLCA1, and IL-33 display a distinctly high non-specific relationship with allergic and non-allergic asthma." (PMID 33936056, 2021).
breast carcinoma (19 papers, 2012 to 2025). "In our study, only one case showed significant expression of MUC5AC, consistent with a previous study that showed MUC5AC expression in < 10 % of breast cancer cases." (PMID 27846863, 2016). "Moreover, increased MUC5AC expression was observed in breast cancer brain metastasis through c-MET signaling." (PMID 41369362, 2025). "For instance, PHTF1, ZNF192, and MUC5AC are already shown to be involved in breast cancer." (PMID 29589558, 2018). "However, to our best knowledge, expression of MUC5AC has so far neither been linked to invasive breast cancer nor been reported as a potential target of Wnt5a signaling." (PMID 28695110, 2017). "For diagnostics purposes, antibodies associated with breast carcinoma include estrogen receptor (ER), progesterone receptor (PR), gross cystic fluid protein (GCDFP), HER-2/neu, cytokeratins (CK5/6, CK7, CK20), and the mucin glycoprotein antibodies, namely, MUC2, MUC3, MUC5AC, MUC6, and DAS-1." (PMID 24066246, 2013). "MUC5AC and MUC6 share similar functions in protecting the mucosal membrane; however, reports on their expressions in breast cancer are limited." (PMID 27846863, 2016). "We have described clinicopathological characteristics of patients with breast cancer containing SRCs in relation to the expression levels of MUC1, MUC2, MUC4, MUC5AC, and MUC6." (PMID 27846863, 2016). "In breast cancer, most tumors express MUC1 and MUC3, and the expression of MUC2, MUC4, MUC5AC, and MUC6 is variable or limited." (PMID 27846863, 2016). "Among the four polymerizing mucins MUC2, MUC5B, MUC5AC, and MUC6 whose altered expression has been reported in breast cancer tissues, the role of MUC5B is poorly documented." (PMID 23056409, 2012). "It has capability to downregulate ERK which may induce Mucin 5AC (MUC5AC) secretion, and it can be useful in treatment of breast cancer." (PMID 40143206, 2025). "Blocking the MUC5AC/c-MET/CD44v6 complex with a blood–brain barrier-permeable c-MET inhibitor, bozitinib, effectively reduces MUC5AC expression and decreases the metastatic potential of breast cancer cells to the brain." (PMID 41369362, 2025). "Six variants had no additional breast-cancer-affected carriers identified in the pedigrees they were originally found in (in genes KIF15, TMEM192, MUC5AC, TEP1, ZFX, and TNN)." (PMID 38136396, 2023). "Important tumor types with low or absent MUC5AC immunostaining included sarcomas, lymphomas, endocrine tumors, renal cancer, breast cancer, prostate cancer, and various skin tumors." (PMID 34547930, 2021). "For instance, PHTF1, MUC5AC, ZNF192, PCSK6, and HDGFRP3 are shown to be involved in breast cancer, and some common genes such as DCT, ZP2, and CEACAM7 might be involved in breast cancer." (PMID 29589558, 2018). "While markers usually positive in gastric adenocarcinoma such as cytokeratin 20, CDX2, MUC5AC, and Hep Par 1 were negative, those supporting breast carcinoma (estrogen and progesterone receptors, cytokeratin 7, and GATA3) decorated the cancer cells." (PMID 25400965, 2014).
mucinous adenocarcinoma (19 papers, 2012 to 2025). An invasive adenocarcinoma composed of malignant glandular cells which contain intracytoplasmic mucin. "In LUAD, MUC5AC expression is notably linked to aggressive subtypes such as Invasive Mucinous Adenocarcinomas (IMA)." (PMID 40655139, 2025). "We find that (BPI) fold-containing family B member 1 (BPIFB1) is the most significantly increased secretome-associated protein in UIP, whereas Mucin-5AC (MUC5AC) is the most significantly increased in mucinous adenocarcinoma." (PMID 37005656, 2023). "Glycan variants of MUC5AC such as Sialyl-Lewisa (SLea), Sialyl-Lewisx (SLex), STn, and Thomsen-Friedenreich (T) (STn/T/SLea/SLex-MUC5AC) have been associated with mucinous adenocarcinomas from the stomach, ampulla of Vater, colon, lung, breast & ovary." (PMID 34205412, 2021). "For instance, a t-SNE cluster enriched for KRAS-mutant cases exhibited high expression of both HNF4A and MUC5AC, which are expressed at high levels in invasive mucinous adenocarcinoma, a distinct histological subtype of LADC18." (PMID 41198678, 2025). "Central to the airway mucin composition, MUC5AC and MUC5B are intimately associated with invasive mucinous adenocarcinoma of the lung." (PMID 40655139, 2025). "We found that in grade 3 non-mucinous adenocarcinomas (n = 56), sex, pleural invasion, pStage, HNF4α expression and MUC5AC expressions, were poor prognostic factors (Online Resource 6a)." (PMID 38710944, 2025). "With regard to the mucus phenotype of each lesion, the IAPN was MUC2 and MUC5AC positive, while the mucinous adenocarcinoma was MUC2-positive and MUC5AC-negative." (PMID 33452648, 2021). "MUC5AC expression has been noted in many CRCs, most often in mucinous carcinomas." (PMID 36900282, 2023). "Additionally, markers of invasive mucinous adenocarcinoma (MUC5AC, MUC5B, SPDEF, FOXA3) were highly expressed in organoids, retaining the histological characteristics of the patient’s original tumor." (PMID 37508518, 2023). "Thus, a distinguishing factor for fibrotic/UIP mucus is the high abundance of MUC5B and BPIFB1, whereas MUC5AC is predominant in mucinous adenocarcinoma mucus." (PMID 37005656, 2023). "Lack of MUC5AC staining was observed for two high-grade mucinous adenocarcinomas, indicating a loss or lowered expression of MUC5AC in cancer cells with high differentiated grade." (PMID 26075384, 2015). "Interestingly, overexpression of EGF receptor 2 (ERBB2, HER2) has been demonstrated in primary lung mucinous adenocarcinomas, which were characterized by KRAS activating mutations as well as very high levels of MUC5AC production." (PMID 22676183, 2012). "Instead, activation status of EGF receptors might be more important, while in mucinous adenocarcinomas, the constitutive activation of the ERBB2 pathway, which is caused by persistent up-regulation of ERBB2 and ERBB2 mutations, might contribute to the MUC5AC overexpression." (PMID 22676183, 2012). "Mucinous adenocarcinoma showed less MUC1 expression with lower IRS scores and higher MUC5AC expression." (PMID 36367122, 2023). "In our study, mucinous adenocarcinoma differed from other histologic subtypes regarding MUC1 and MUC5AC expression." (PMID 36367122, 2023). "To validate this result, we performed immunofluorescence on both mucinous adenocarcinoma (n = 3) and UIP specimens (n = 4) for MUC5B, MUC5AC, and BPIFB1." (PMID 37005656, 2023). "Mucinous adenocarcinoma differed from other histologic subtypes regarding MUC1 and MUC5AC expression." (PMID 36367122, 2023). "Mucinous adenocarcinoma (a more aggressive LC subtype) showed higher expression of secretory mucins, including MUC2, MUC5AC, and MUC6." (PMID 36980526, 2023). "In 9 cases of mucinous adenocarcinoma (NOS), the expression rate of MUC5AC and CK7 were both 88.88% (8/9)." (PMID 32843061, 2020). "Adenocarcinomas in FOXM1 transgenic mice expressed increased MUC5B and MUC5AC, and reduced NKX2.1, which are characteristics of mucinous adenocarcinomas." (PMID 29267283, 2017).
mucinous adenocarcinoma (continued). "The expression of MUC5AC in the high-grade mucinous tumor cells seemed to be lower compared to benign, LMP and low-grade mucinous adenocarcinomas." (PMID 26075384, 2015). "Conversely, Mucin5AC (MUC5AC) is almost not expressed in colorectal-origin mucinous carcinomas, but shows diffuse positive expression in primary MOC, with an expression rate of 86%." (PMID 39040449, 2024). "Inversely, mucinous adenocarcinoma mucus was positive for MUC5AC, whereas MUC5B and BPIFB1 are largely negative at the immunofluorescence level (white arrows point where MUC5B/BPIFB1 are absent)." (PMID 37005656, 2023). "Similar results were found for MUC5AC in 10 mucinous adenocarcinomas (mBAC) (100%), but not for MUC2 (0%) in another study." (PMID 36367122, 2023). "Increased MUC5AC were specific makers for non-terminal respiratory unit adenocarcinoma, including both mucinous adenocarcinoma and central type adenocarcinoma." (PMID 28938681, 2017). "In a study comparing 7 mucinous adenocarcinomas (previously known as mucinous bronchioloalveolar carcinoma (mBAC)) and 27 non-mucinous BAC, higher levels of MUC2, MUC5AC, and MUC6 expression were found in mucinous BAC." (PMID 36367122, 2023). "On the other hand, mucinous adenocarcinoma component was positive for MUC2, and negative for MUC5AC and CD10, indicating the intestinal type." (PMID 33452648, 2021).
adenoma (17 papers, 2006 to 2025). A neoplasm arising from the epithelium. "In adenoma-carcinoma sequence, with facing to persistent MUC5AC antigenity caused IgG type immune response." (PMID 16409634, 2006). "Of the 120 colonic polyps they evaluated, which ranged from 0.5 cm to greater than 2 cm, adenomas with villous features had a higher percentage of MUC5AC expression at 40.7% (n = 86) compared to that of 24% for tubular (n = 25)." (PMID 36900282, 2023). "The adenoma tissue was diffusely positive for MUC5AC, while MUC6 was focally positive, indicating that the epithelium that composed the adenoma was a gastric foveolar phenotype." (PMID 35508985, 2022). "To clarify what types of adenomas are associated with GDM, we performed IHC for CDX-2 (a marker of intestinal origin), MUC5AC (a marker of gastric foveolar mucin), and MUC6 (a marker of gastric pyloric gland mucin)." (PMID 28467793, 2017). "More undifferentiated gastric tumors tend to increase expression of CTSE and MUC5AC in tumor lesions (tub2> tub1> adenoma) but decrease expression of these gastric markers in the background mucosa (tub2< tub1< adenoma)." (PMID 23451082, 2013). "While these two mucins were reported previously to be more expressed in medium size/stage adenomas, more recent data reports MUC5AC to be involved in early stages of malignant transformation, and MUC6 in final stages." (PMID 20929551, 2010). "Overall incidence of MUC5AC was observed to be in 63% adenoma cases." (PMID 32168759, 2020). "More than 50% of serrated adenomas had MUC5AC expression level of 2+ or more." (PMID 20929551, 2010). "In contrast, gastric-type tumors showing negative nuclear expression of β-catenin were identified as FAs, and the adenocarcinomas consisted of MUC5AC-positive atypical cells and NOS-type adenomas." (PMID 40463821, 2025). "The values of Ripley’s H indicate spatial attraction between MUC5AC+ and CD68+ cells in SSLs, but spatial repulsion between these two in adenomas." (PMID 38833684, 2024). "The other 21 adenomasshowed nuclear β-catenin expression and these were all intestinal-type adenomas identified with expressions of CDX2(+), MUC5AC(-), and MUC6(-)." (PMID 28467793, 2017). "Two foveolar-type adenomas showed CDX-2(-), MUC5AC(+), MUC6(-), and 2 pyloric gland adenomas showed CDX-2(-), MUC5AC(-), MUC6(+)." (PMID 28467793, 2017). "However, a focal gastric differentiation, supported by MUC5AC and MUC6 expression, may be present in otherwise typical intestinal-type adenomas." (PMID 33922305, 2021). "MUC5AC is positive in hyperplasia and negative in adenoma and adenocarcinoma." (PMID 31728658, 2019). "MUC5AC and MUC6 were also found in a high proportion of villous and tubulovillous adenomas but not in normal colonic biopsies." (PMID 26500890, 2015). "Expression scores of CTSE, MUC5AC, and MUC2 (from 1 to 4 respectively) in gastric tumors cells (cancer or adenoma) and adjacent normal cells (non-tumorous epithelial cells of background mucosa)." (PMID 23451082, 2013).